GPR84 (G protein-coupled receptor 84)
Diseases named in the same sentence as GPR84 in open-access papers (continued):
Sharing a sentence is not in itself a finding about the gene and the disease.
cancer (17 papers, 2016 to 2025). A tumor composed of atypical neoplastic, often pleomorphic cells that invade other tissues. "Orphan G-protein-coupled receptor 84 (GPR84) is a receptorthathas been linked to cancer, inflammatory, and fibrotic diseases." (PMID 38146625, 2024). "This adoptive transfer of myeloid cells models further verified that GPR84 deficiency dominantly inhibited MDSCs accumulation and function to reverse the immunosuppressive tumor microenvironment and enhance the prognosis of malignant tumors." (PMID 37105980, 2023). "Finally, we screened drug targets based on the immune index defined by CD45 expression and identified that the immune-related gene GPR84 affected the proliferation of cancer cells and was associated with the inflammation brought during immunotherapy." (PMID 36061172, 2022). "In a study published in Nature, researchers used intercellular CRISPR screening to identify PRFs in cancer cells, and using genome-wide reverse screening in macrophages, they found that the G-protein-coupled receptor GPR84 mediates enhanced phagocytosis in APMAP-deficient cancer cells." (PMID 35706452, 2022). "However, we also noticed that blockade of IL-11 can only partially reverse the downregulated expression of GPR84 caused by cancer CM, implying that some other unknown components in CM inhibited the level of GPR84, which should be further investigated." (PMID 36593458, 2023). "In view of the mouse cancer models performed later in this study, we explored the effects of the GPR84 agonist 6-OAU on murine BMDMs." (PMID 39859206, 2025). "Current GPR84 agonists lack efficacy in promoting anti-cancer macrophage activity, limiting their potential as CRC therapies." (PMID 39859206, 2025). "The inability to replicate previous results underscores important gaps in our understanding of GPR84’s role in cancer therapy and highlights the need for careful refinement of experimental designs, agonist selection, dosing regimens, and model systems." (PMID 39859206, 2025). "Together, our findings offer new insights into an underappreciated fatty acid receptor, GPR84, in the context of macrophage-mediated immunity against cancer." (PMID 38349405, 2024). "Our analysis has demonstrated for the first time the connection between GPR84 and anti-tumorigenic macrophage signatures in the human cancer dataset." (PMID 38349405, 2024). "Among those we identified as globally dysregulated in cancer, the medium-chain fatty acid receptor GPR84 was significantly upregulated in fourteen out of the twenty-three cancer types examined, highlighting this receptor as a promising biomarker." (PMID 39766077, 2024). "Loss of the APMAP gene can significantly enhance the macrophage phagocytosis of cancer cells, which is dependent on GPR84 and Gi12." (PMID 37709767, 2023). "Altogether, our data suggested that activation of the GPR84-Gi signaling axis in macrophages can synergize with CD47 blockade to drive the phagocytosis of cancer cells." (PMID 37709767, 2023). "In this study, we show that the activation of GPR84 by the synthetic agonist 6-OAU can synergize with the blockade of CD47 on cancer cells to induce phagocytosis of cancer cells by macrophages." (PMID 37709767, 2023). "All the data suggested a critical role of the GPR84-Gi signaling axis in mediating phagocytic activities of macrophages especially TAMs against cancer cells." (PMID 37709767, 2023). "In the natural progression of cancer bone metastasis, the expression of GPR84 was downregulated in the tumor microenvironment; however, activation of GPR84 through 6-OAU, a potent agonist, inhibited osteolysis." (PMID 36593458, 2023). "Immunofluorescence investigations confirmed that GPR84 was highly expressed in the CD33+ MDSCs of cancer tissues." (PMID 37105980, 2023). "We expect that our results will facilitate future drug development on GPR84 for cancer and other inflammatory diseases." (PMID 37709767, 2023).
cancer (continued). "During bone metastasis of CRC, the expression of GPR84 was highest in normal BMMs, and then the expression level decreased gradually with the progression of cancer bone metastasis." (PMID 36593458, 2023). "The dbSNP database and the Catalogue of Somatic Mutations in Cancer (COSMIC) revealed 275 SNPs in human GPR84 causing an altered coding sequence." (PMID 36164652, 2022). "Further, mouse models featuring other cancer entities could help to evaluate the anti-cancer effect of synthetic GPR84 agonists." (PMID 39859206, 2025). "Meanwhile, another mono/macrophage cluster with heightened FN1 levels, which is associated with pro-angiogenic TAMs and necessary for cancer metastasis, was amplified in the tumor-bearing mice lacking Gpr84." (PMID 38349405, 2024). "Next, we investigated whether GPR84 can also be regulated by IL-11 in vivo during cancer bone metastasis." (PMID 36593458, 2023). "Furthermore, we demonstrated that the Gi signaling pathway is critical in the phagocytic function of GPR84 against cancer cells." (PMID 37709767, 2023). "Gi pathway-selective GPR84 agonists, or Gi-biased GPR84 agonists, may offer an interesting therapeutic method to enhance the phagocytosis of cancer cells by macrophages." (PMID 37709767, 2023). "In this regard, selective activation of the GPR84-Gi pathway with minimal β-arrestin recruitment by Gi-biased GPR84 agonists such as DL-17521 or PSB-1667151 may promote more sustained macrophage phagocytosis of cancer cells compared to 6-OAU." (PMID 37709767, 2023). "Together, these results indicated that activating GPR84 could prevent osteoclast formation in cancer bone metastasis." (PMID 36593458, 2023). "In this study, we first showed that the activation of GPR84 by the synthetic agonist 6-OAU could synergize with the blockade of CD47 on cancer cells to induce phagocytosis of cancer cells by macrophages." (PMID 36824923, 2023). "Therefore, evaluation of the clinical data of patients with malignant tumors demonstrated that the GPR84 signature was positively correlated with resistance to anti-PD-1 therapy." (PMID 37105980, 2023). "In addition, the membrane-embedded enzyme APMAP that is highly expressed on the surface of cancer cells has been proposed to degrade the physiological lipid ligand of GPR84 to negatively regulate macrophage phagocytosis." (PMID 37709767, 2023). "Moreover, we identified that IL-11 derived from cancer cells at least partially inhibits the expression of GPR84 in OCPs by inactivating STAT1." (PMID 36593458, 2023). "Therefore, orthotopic mouse models of CRC might be more adequate and informative to evaluate the anti-cancer potential of synthetic GPR84 agonists." (PMID 39859206, 2025). "Interestingly, the effect of CM on the level of GPR84 was significantly reversed in the presence of IL-11 NAb, indicating that blocking the endogenous IL-11 secreted by cancer cells could regulate the expression of GPR84." (PMID 36593458, 2023). "Therefore, GPR84 stimulation–mediated mechanisms of action in BAT for cancer metabolism and AD could be an interesting topic for future studies." (PMID 37856216, 2023). "This study evaluates the effects of the GPR84 agonists 6-OAU and ZQ-16 on macrophage activation and anti-cancer efficacy." (PMID 39859206, 2025). "Pharmacological agonists of GPR84 hold promise to reshape and reverse the immunosuppressive TME, and thereby restore responsiveness of cancer to overcome resistance to immune checkpoint blockade." (PMID 38349405, 2024). "Recently, biased GPR84 agonists like 6-OAU and ZQ-16 were developed, showing potent activation of GPR84 and promoting pro-inflammatory responses in macrophages, such as cytokine production, migration, and phagocytosis of cancer cells." (PMID 39859206, 2025). "GPR84, a G protein-coupled receptor (GPCR) primarily expressed on immune cells, may be a promising target for cancer treatment." (PMID 39859206, 2025).
cancer (continued). "In particular, the ability of the GPR84 agonist 6-OAU to promote phagocytosis of cancer cells induced by CD47 blockage and the specific expression of GPR84 in TAMs12 implied a potential role of GPR84 in cancer immune surveillance." (PMID 37709767, 2023). "High correlation between expression level of GPR84 and CD45 was also observed across cancers." (PMID 36061172, 2022). "However, antibody-dependent phagocytosis of cancer cells was not enhanced by GPR84 agonism." (PMID 39859206, 2025). "Identifying such a ligand of GPR84 and APMAP may lead to the identification of a novel pathway regulating macrophage function and facilitate the development of novel therapeutics targeting this pathway in addition to GPR84 activators to enhance cancer cell phagocytosis." (PMID 37709767, 2023). "Despite the negative data presented in the current study, GPR84 remains an interesting candidate to be explored in the context of CRC and other cancer entities." (PMID 39859206, 2025).
tumor (12 papers, 2014 to 2025). "As a result, GPR84 deficiency accelerates tumor growth with augmented immunosuppressive TAMs and dampened CD8 T cell function." (PMID 38349405, 2024). "To investigate the transcriptional programs that underlie this difference, we performed scRNA-seq on tumor-infiltrating immune cells from Gpr84+/+ and Gpr84−/− MC38 tumor-bearing mice on day 21 past inoculation." (PMID 38349405, 2024). "Overall, these data suggest that loss of Gpr84 in macrophages enhances tumor progression by favoring immunosuppressive TAMs and restricting CD8 T cells within the TME." (PMID 38349405, 2024). "To understand the underlying mechanism by which GPR84 inhibits osteoclastogenesis in the tumor microenvironment, we detected several intracellular pathways associated with osteoclastogenesis that are regulated by GPR84." (PMID 36593458, 2023). "Herein, we observed that loss of GPR84 restrained tumor growth, consistent with a role for GPR84 in solid tumor progression." (PMID 37105980, 2023). "For further exploring the mechanism underlying GPR84 promoting MDSCs suppression, whole-genome RNA sequencing was performed on tumor tissues derived from WT and GPR84−/− LLC model." (PMID 37105980, 2023). "GPR84 deficient (GPR84−/−) mice were generated to evaluate their role in tumor development." (PMID 37105980, 2023). "In addition, we screened drug targets based on the immune index defined by CD45 expression and identified that GPR84 affected the proliferation of tumor cells and was associated with the inflammation caused by immunotherapy." (PMID 36061172, 2022). "Previous publications reported that GPR84 activation promotes macrophage-mediated tumor cell phagocytosis." (PMID 39859206, 2025). "Altogether, these findings suggest that GPR84 endorses anti-tumor immunity by inducing pro-inflammatory TAMs via the STAT1 pathway and that targeting this pathway can improve the efficacy of ICB." (PMID 38349405, 2024). "All of these results suggest that the expression of GPR84 is limited to tumor-infiltrating myeloid cells." (PMID 38349405, 2024). "Within the tumor, the majority of GPR84 proteins (more than 90%) are restricted to MDSCs and macrophages, whereas only 5% of GPR84 is found in other immune cells (Supplemental 1F–H)." (PMID 38349405, 2024). "From an unbiased analysis of single-cell transcriptome data from multiple tumor models, we discovered that anti-tumorigenic TAMs uniquely express elevated levels of a specific fatty acid receptor, G-protein-coupled receptor 84 (GPR84)." (PMID 38349405, 2024). "More intriguingly, GPR84 deficiency reduces activity in both the complement and antigen presentation pathways on MC38 tumor model." (PMID 38349405, 2024). "More importantly, the flow cytometry results showed that the proportion of MDSCs in spleen, tumor tissues and blood in GPR84−/−→WT group were decreased." (PMID 37105980, 2023). "Flow cytometric analysis of peripheral blood and tumor tissue from ESCC patients demonstrated that GPR84 was highly expressed in polymorphonuclear-MDSCs (PMN-MDSCs) than monocytic-MDSCs (M-MDSCs)." (PMID 37105980, 2023). "We found high expression of GPR84 in the tumor tissues of PCa patients, the mRNA expression level of GPR84 was significantly increased in PC3 cells after being treated with high concentration of FFA C8:0." (PMID 37170248, 2023). "Herein, we found that GPR84 was a new target of IL-11 that stimulates osteoclast formation in the tumor microenvironment, providing a novel mechanism in IL-11-mediated osteoclastogenesis." (PMID 36593458, 2023). "In order to further verify that GPR84 promotes tumor progression mainly by increasing the number and function of MDSCs, the adoptive transferred of myeloid cell model was used." (PMID 37105980, 2023). "In GPR84−/− mice treated with anti-PD-1, tumor volume was significantly reduced, and immunosuppression-related genes in MDSCs from tumor tissues were significantly downregulated." (PMID 37105980, 2023).
tumor (continued). "It was further found that GPR84 was prominently expressed on MDSCs in clinical samples and tumor mouse models, which drives the immunosuppression on CD8+T cells by inhibiting PD-L1 degradation in lysosomes." (PMID 37105980, 2023). "GM-CSF and G-CSF were also identified to enhance the expression of GPR84 in MDSCs derived from bone marrow cells of tumor-free mice." (PMID 37105980, 2023). "Using GPR84−/− mice or GPR84 antagonist, we found that tumor progression was inhibited dependent on the prevention of MDSCs immunosuppressive activity." (PMID 37105980, 2023). "Our investigations of tumor tissues from ESCC patients by immunohistochemical demonstrated that increased expression of GPR84 significantly shortened the patients’ overall survival." (PMID 37105980, 2023). "The results showed that the proliferation and clone formation ability of tumor cells decreased significantly after neutralizing the function of GPR84." (PMID 36061172, 2022). "Through immunohistochemical staining, we found that the proteins encoded by GPR84 and NCF2 were significantly increased in tumor core, further suggesting a pro-tumoral role of these genes." (PMID 36177003, 2022). "Further studies are required to understand the mechanism of GPR84 function in the tumor microenvironment, and validate its role as a novel drug target to suppress inflammation." (PMID 36061172, 2022). "Last, the precise mechanism of GPR84 upregulation in TAMs still remains unclear, which prompts future studies to identify the tumor-derived factors that drive the expression of GPR84." (PMID 38349405, 2024). "To test this idea, we sought to investigate whether therapeutic activation of GPR84 promotes anti-tumor responses and synergizes with PD-1 blockade." (PMID 38349405, 2024). "Similarly, the mono/macrophage cluster with higher expression of Cxcl10, which is a key chemokine responsible for CD8 T cell recruitment in tumor, are reduced in in Gpr84−/− mice." (PMID 38349405, 2024). "Consequently, we observed a subverted effector signature in CD8 T cells and accelerated tumor progression in Gpr84−/− mice." (PMID 38349405, 2024). "Single-agent treatment of GPR84 with the activator 6-OAU delayed the tumor growth significantly." (PMID 38349405, 2024). "Therefore, the discovery of the main endogenous ligands in the tumor that are responsible for GPR84 activation in TAMs is needed." (PMID 38349405, 2024). "Additional investigation is warranted to determine whether the anti-tumor effect of GPR84 activation is independent on the impact of GPR84 on tumor- infiltrating neutrophils." (PMID 38349405, 2024). "Among these tumor-enriched genes, fatty acid sensor, GPR84, is predominantly upregulated in the tumor-infiltrating macrophages cells, but barely detectable in adjacent benign tissues, peripheral blood mononuclear cells and other immune cells such as innate lymphoid cells (ILCs), T, and B cells." (PMID 38349405, 2024). "In addition, activation of the ERK, JNK or p38 MAPK pathways using agonists efficiently reversed the inhibitory effect of overexpressing GPR84 on osteoclast formation in the tumor microenvironment." (PMID 36593458, 2023). "To further explore the effect of GPR84Y370H variant on GCs, we constructed the GPR84Y370H overexpressed (shown as GPR84WT/mut) and GPR84 overexpressed (shown as GPR84WT/WT) stable cell lines in KGNs (human granulosa-like tumor cell line), while the GPR84WT/WT group was regarded as the control." (PMID 37065482, 2023). "Anti-PD-1 treatment notably reduced tumor growth and prolonged the survival of GPR84−/− mice." (PMID 37105980, 2023). "Besides, the mRNA expression level of GPR84 in tumor tissues of PCa patients was also significantly increased." (PMID 37170248, 2023). "Next, the GPR84 antagonist was further used to verify the effects on tumor microenvironment." (PMID 37105980, 2023).